CD24 (CD24 molecule)
Diseases named in the same sentence as CD24 in open-access papers (continued):
Sharing a sentence is not in itself a finding about the gene and the disease.
tumor (continued). "However, as observed in ER+ disease, CD44+CD24-/low positive tumours were more often node-negative in ER- cases also, with 64% of CD44+CD24-/low positive tumours being node-negative compared to 51% of CD44+CD24-/low negative cases (P = 0.012)." (PMID 22112299, 2011). "Similarly, 68% of CD44+CD24-/low positive tumours were node negative, compared to 60% of CD44+CD24-/low negative cases (P = 0.008)." (PMID 22112299, 2011). "For instance, breast cancer cells expressing either no or low levels of single chain sialoglycoprotein CD24 in combination with CD44-positivity have been identified as CSCs, whereas in pancreas and colon, the CD24high cells were shown to contain the tumor-initiating fraction." (PMID 21311095, 2010). "The expression of certain cell surface marker proteins, CD24, CD44 and CD227, was maintained during long term tissue culture-derived HBCEC, demonstrating that the extended culture conditions of the tumor tissue did not affect the expression of these adhesion molecules in the HBCEC." (PMID 19751512, 2009). "Examination of the injection sites where CD44+/CD24+/ESA+ and CD44+/CD24-//ESA- cells were unable to form tumors revealed viable cells and Matrigel at the site of injection (data not shown), confirming that lack of tumor growth from these cells was not due to clearing or cell death." (PMID 18366788, 2008). "However, in CD24−/CD44+‐breast CSCs xenotransplanted group treated with a low dose of doxorubicin and the potent EGFR inhibitor/compound 1e, normal morphology of mammary gland with subcutaneous fat was observed with no tumor mass." (PMID 38522013, 2024). "The expression of inducible nitric oxide synthase in CD24+CD133+ LCSCs, but not CD24−CD133− LCSCs, has been found to promote stemness characteristics of LCSCs via Notch1 signaling, and to accelerate HCC initiation and tumor formation in a mouse xenograft tumor model." (PMID 38009775, 2023). "We first established that the promoter methylation of CD44, CD24, CD147, and CD133 was absent in normal oral mucosal tissues (n = 45), indicating that the methylation of these genes may represent an abnormal event in tumor cells." (PMID 36498950, 2022). "Thus, CD24 and NF-κB could be participating in a negative feedback that ultimately determines the final CSC fraction of a tumor." (PMID 27876836, 2016). "However, similar to ER PR data, the IL-6 data suggest that tamoxifen and aromatase inhibitors would likely target the largest tumor BCSC population represented by CD49f−CD24−(MM), but not the scarce stem/progenitor populations represented by CD49f+CD24+(PP), CD49f+CD24−(PM) or CD49f−CD24+(MP) cells." (PMID 25269750, 2014). "To test whether culturing tumor cells in non-adherent condition could affect methylation of the genes analyzed, we also subjected sorted subpopulations of SUM159 cells (ALDH+, ALDH-, CD44+CD24-, CD44+CD24+) to gene methylation analysis." (PMID 23883436, 2013). "Furthermore, the method for identification of CD44-/CD24- TNBC cells did not include a positive tumor molecular marker, which might contaminate some other types of cells, although using histological tissue sections for identification of tumor cells." (PMID 34318746, 2021). "For instance, in the HER2-OE cell line SK-BR-3, the CD44/CD24 ratio was low, whereas the expression level of ALDH1 was high, suggesting that single CSC marker alone might not be enough to characterize tumor stemness or to evaluate tumor malignancy and prognosis." (PMID 29062075, 2017).
cancer (1,044 papers, 2001 to 2026). A tumor composed of atypical neoplastic, often pleomorphic cells that invade other tissues. "CD44 is linked to stem cell characteristics, whereas CD24 expression is associated with cancer cell differentiation." (PMID 39932626, 2025). "Growing clinical evidence suggests that patients expressing high levels of CD24 are at a higher risk of disease progression and cancer-related death." (PMID 40486886, 2025). "The system also enriched cancer stem-like properties, with higher expression of stemness-associated genes (CD24, CD44, CD133, ALDHA1, CXCR4, Sox2, Oct4, Nanog, and KLF4) and expansion of CSC populations expressing (CD44, CD90, CD117, EpCAM, and CK19)." (PMID 41149589, 2025). "In the murine 4T1 model, both CD44+CD24− and CD44+CD24+ populations have been positively associated with cancer-initiation potential, illustrating model-specific variability in CD24’s function." (PMID 40783744, 2025). "Common markers include EpCAM, used for epithelial cancers; CD44 and CD24, which are associated with cancer stem cells; and cytokeratins, such as CK8 and CK18." (PMID 40260304, 2025). "The (CD44+/CD24-) SKOV3-derived “twin” cells lack expression of CD24, often associated with cancer stemness." (PMID 39592661, 2024). "Gene association and enrichment analyses showed that CD24/SOX4-centered signaling hub was associated with cancer cell metabolism, immune responses, ECM regulation, and Wnt/β-catenin pathways." (PMID 38203779, 2024). "We also observed a significant reduction in EMT-associated genes and cancer stemness-associated genes and increase in E-Cadherin and epithelial cell marker CD24 when OSMR is knocked down in both OVCAR8-CisR and A2780-CisR resistant cells." (PMID 38839865, 2024). "More and more evidence confirms that the expression of CD24 in cancer is associated with poor prognosis and promotes malignant progression of tumors in a dose-dependent manner." (PMID 38914670, 2024). "CD24 can contribute to cancer progression as a surface receptor associated with various downstream networks." (PMID 38360723, 2024). "Our study has unraveled a unique association between LGMN/SPP1+ TAMs and stemness-related cancer cells (cancer cell cluster C6 marked by co-expression of CD24, CD47 and ICAM1)." (PMID 38169544, 2024). "Nonetheless, further studies are necessary to fully elucidate the precise functions of CD24 in cancer pathogenesis and the underlying mechanisms at play." (PMID 38881902, 2024). "CD24 is a small, highly glycosylated membrane protein whose expression is associated with tumorigenesis and the progression of several types of cancer." (PMID 39687458, 2024). "The majority of GD2+ cells are also CD44 and CD24 positive and previously considered to associate with cancer stem cell surface phenotypes." (PMID 38731901, 2024). "CD24 overexpression in multiple cancer cell types is associated with the development and progression of cancer, resulting in poor prognosis." (PMID 37894750, 2023). "Typically, elevated CD24 expression is associated with cancer progression and poor prognosis in hematologic cancers such as B cell-derived lymphoma and multiple myeloma (MM)." (PMID 37894750, 2023). "The association between CD24 and cancer stem cells has been proved in various types of cancer, including breast cancer, ovarian cancer, pancreatic cancer, hepatocellular carcinoma, bladder cancer, melanoma, colon cancer, leukemia, and multiple myeloma." (PMID 38313430, 2023). "CD24 is overexpressed in many cancers and some cancer stem cells and is associated with the development, invasion, and metastasis of cancer cells." (PMID 36911388, 2023). "The discovery that CD24 overexpression was associated with cancer and had demonstrated therapeutic promise from preclinical investigations led to the development of IMM47." (PMID 37846296, 2023).
cancer (continued). "The ability of CD24 on the cell surface to encourage the spread of cancer is associated with its interaction with P-selectin, which is found on stimulated platelets and the cells lining blood vessels." (PMID 38313430, 2023). "In cancer, CD24 expression is strongly associated with reduced life expectancy and is used as a diagnostic marker for patient prognosis." (PMID 37524694, 2023). "Studies have demonstrated that CD24 is a diagnostic biomarker for poor prognosis of ovarian and other cancers." (PMID 36741380, 2022). "CD24 is a small and heavily glycosylated mucin-like glycosylphosphatidyl-inositol-linked cell surface protein, was detected in several types of carcinomas but is rarely expressed in normal tissues." (PMID 35037689, 2022). "CD24 is a well-established marker overexpressed in various carcinomas, where it is associated with poor survival." (PMID 35625912, 2022). "In many human cancers, CD24 overexpression is highly associated with adverse prognostic features such as lymph node metastases, advanced clinical stage and shorter overall survival." (PMID 33588867, 2021). "CD44+/CD24- expression is associated with cancer stem like properties, chemoresistance and more invasive capacity." (PMID 32544183, 2020). "Recently, several studies have shown enhanced CD24 expression in various cancers including RB, where CD24 expression is associated with severity of disease." (PMID 32394616, 2020). "CD24 has been implicated in the pathogenesis of a wide range of human cancers and emerged as a novel anticancer application in a panel of solid cancers." (PMID 33298865, 2020). "CD24 is a glycosyl-phosphatidyl-inositol linked glycoprotein expressed in a broad range of cell types including cancer cells." (PMID 31244889, 2019). "Studies have demonstrated that higher CD24 expression is associated with shorter patient survival, making CD24 a significant prognostic marker for malignant tumors." (PMID 31614769, 2019). "Of broader interest, CD24 is expressed in a variety of human cancers and is associated with poor survival." (PMID 30717444, 2019). "CD24 plays several critical roles in cancer pathogenesis and cell surface CD24 has long been associated with cancer metastasis through its role as selectin ligand." (PMID 31244889, 2019). "Previous studies have shown that CD24 is mostly associated with drug resistance as a cancer stem cell marker molecule." (PMID 29844385, 2018). "The role of m-CD24 in cancer progression seems complicated with some studies show promotion role, while others associate c-CD24 instead with cancer progression." (PMID 28052035, 2017). "Significantly, molecular targeting of SMAD5 expression was linked to inhibition of a CD44+/CD24-/PROCR+ cancer stem cell-like phenotype and low ALDH1 activity." (PMID 29207686, 2017). "CD24 is an anchored cell surface marker that is highly expressed in cancer cells and its expression is associated with poorer outcome of cancer patients." (PMID 26484297, 2015). "CD24 is a multifaceted protein implicated in inflammation, immunity—both adaptive and autoimmunity—and cancer." (PMID 26039238, 2015). "The results showed that stemness genes (Nanog and Oct-4), multiple drug-resistant transporter gene (ABCG2) and surface antigens associated with cancer stem cells (CD24, CD44 and CD133) were upregulated in ZIPK-transfected cells compared with control cells." (PMID 25831050, 2015). "In many cancers, such as colorectal, pancreas, and lung, high expression of CD24 is associated with enhanced invasiveness and proliferation." (PMID 26301220, 2015). "Basal B cell lines, like MDA-MB-231 or SUM159PT have a mesenchymal-like phenotype and features of cancer stem cells (CD44+ CD24−/low, ALDH1+), indicating that Cyr61 is associated with a more aggressive phenotype." (PMID 25980494, 2015). "Ras is an oncogene with mutations present in approximately 30% of all human cancers and has been shown to repress CD24 surface expression." (PMID 26301220, 2015).
cancer (continued). "CD24 is a glycosyl phosphatidyl inositol-linked mucin-like cell surface protein with a role in cell adhesion, and is expressed in various cancers." (PMID 25932953, 2015). "The CD24 molecule is a glycosyl-phosphatidylinositol-linked cell surface protein that appears to be associated with aggressive cancers involving invasion and metastasis." (PMID 23946784, 2013). "CD24 positivity and the transcription levels of pro-angiogenic, pro-inflammatory and growth signaling factors in cancer cells are associated with ccRCC invasiveness and metastasis." (PMID 23442546, 2013). "One case of Gleason 4+5 showed, in contrast, strong signals for all cancer-associated markers, including CD24." (PMID 23029164, 2012). "The close association of CD44, CD24 and Oct4 with cancer cell proliferation highly supports the assumption that these are indeed markers of clonogenic cells." (PMID 22333601, 2012). "The present work demonstrates that tumorigenic CD44+CD24−/low (CD24−) cells can originate from primary CD44lowCD24+ (CD24+) human mammary epithelial cells (HMECs) following their transformation with a limited number of oncogenes and cancer-associated genes." (PMID 18682804, 2008). "In patients with locally advanced HNSCC receiving accelerated platinum-based radiotherapy, the widespread presence of CD24+ cancer cells is directly associated with an increased proliferation index and is related to a significantly poorer local progression-free interval." (PMID 40486886, 2025). "A high CD44/CD24 ratio is also linked to the ability of cancer cells to metastasize." (PMID 40227834, 2025). "Moreover, CD24 is implicated in the invasive and metastatic behavior of cancer cells, with its expression significantly elevated at distant metastatic sites compared to primary tumors." (PMID 40223929, 2025). "In addition, CD24 overexpression has been associated with several hallmarks of cancer, including increased cell proliferation, migration, and metastasis." (PMID 40783744, 2025). "Additionally, the MFI of the cancer stemness marker CD24 was significantly associated with the percentage of GSHlo MITOhi CD34+ cells, suggesting a mirrored effect of cell metabolic status on EV surface expression markers." (PMID 39738118, 2024). "Moreover, CD24 expression has also been associated with resistance to chemotherapy and targeted therapies in several cancer types, including breast, ovarian, and pancreatic cancer." (PMID 38881902, 2024). "CD24 expression is associated with CSC phenotype acquisition in various cancers." (PMID 38360723, 2024). "CD24, a cell surface molecule linked to glycosylphosphatidylinositol, is considered an adhesion molecule that facilitates binding with P-selectin and is a characteristic of cancer metastasis." (PMID 38773226, 2024). "Hence, given the findings of these investigations and the known roles of Src kinase in cancer cells, it is suggested that Src kinase plays a pivotal role in the CD24-associated pathways in cancer and in the markers of CSCs." (PMID 38881902, 2024). "In liver cancer, CD24 expression was associated with self-renewal and cancer initiation." (PMID 38360723, 2024). "However, CD24 is also overexpressed in various cancers and is associated with cancer cell invasion, migration, and drug resistance." (PMID 38273373, 2024). "Furthermore, the UPE-induced upregulation of cancer-associated markers (CD24, CD90, and CD133) promotes tumorigenesis and drug resistance." (PMID 39769068, 2024). "The functional properties of CD24 and the genetic or molecular heterogeneity of the cancer cells could cause this dual effect." (PMID 38360723, 2024). "Additionally, CD24 is involved in many cancer metastases, and its expression is associated with differentiated epithelial characteristics." (PMID 37092500, 2023).
cancer (continued). "Therefore, understanding the mechanisms underlying cancer stemness, especially CD24 and chemotherapy resistance is important for providing insights into the development of effective and prospective therapeutic strategies against solid cancers." (PMID 37919766, 2023). "Furthermore, in several cancers, CD24 overexpression was suggested to be significantly associated with shorter patient survival time." (PMID 37919766, 2023). "The CD24–Siglec-10/G interaction constitutes an innate checkpoint that regulates inflammation triggered by danger-associated molecular patterns (DAMPs) and cancer pathogenesis." (PMID 37359556, 2023). "Likewise, HCC1500 cells have been classified as luminal, due to a predominant population of cells that are positive for EpCAM and CD24 or as basal B, owing to an enrichment for gene clusters associated with cancer stem cell and invasive phenotypes." (PMID 36768838, 2023). "Intracellular CD24 is usually linked to cancer and has a distinctive function." (PMID 38137380, 2023). "Cluster of differentiation 24 (CD24), a heavily glycosylated mucin-type glycosylphosphatidylinositol-anchored cell surface molecule, has been verified as highly presented and associated with poor outcomes in human cancers." (PMID 36231025, 2022). "Additionally, in MCF-7 cells, SETD7 knockdown induced the purported cancer stem-like cell phenotype (CD44+/CD24−/low) and dedifferentiation of mammospheres associated with loss of cadherin-1." (PMID 35326563, 2022). "However, depletion of CD24 by siRNA in cell lines from different cancer types decreases cell proliferation rates, causes a variation in the actin cytoskeleton, and induces apoptosis in single cancer cell cultures." (PMID 35625912, 2022). "In TNBC, CD44 + /CD24- phenotypes are associated with cancer stem cells." (PMID 33413403, 2021). "CD24 expression is also associated with enhanced cancer cell adhesion, invasion and metastasis." (PMID 34944851, 2021). "We evaluated the association between CD24/CD11b expression and the subject’s clinical measurements (background diseases, past cancer, family history of cancer, being overweight), healthy behaviors (smoking, physical activity), and demographic characteristics (age, gender)." (PMID 34575716, 2021). "CD24 is also considered a marker for cancer and thus was proposed as a diagnostic tool for cancer." (PMID 33562144, 2021). "A small number of hypoxia-associated genes (APLN, HIF1A, and BNIP3), cancer stem cell (CSC) markers (CD24 and CD44), hormonal regulation (HR) genes (ESR1, PGR, and TFF1), other selected genes (PPARGC1A, ILK), and HKGs (RPL32, GUSB, TBP, OAZ1 and NONO) were also included in the panel." (PMID 34206049, 2021). "Furthermore, recent studies have described CD24 as a putative marker for cancer stem cell (CSC) populations associated with aggressive cancer types and poor prognoses." (PMID 32513298, 2020). "In this respect, a recent report on the suppression of cancer cell phagocytosis by macrophages via interaction between CD24 and Siglec-10 (on cancer cells and tumor-associated macrophages, respectively) may provide an insight." (PMID 31900164, 2020). "A similar reason may underlie decreased expression of ALDH1A1 and CD24, cancer stem cell-like markers commonly associated with more aggressive features and EMT phenotype, seen in CR samples." (PMID 32899940, 2020). "As the researchers suggested, a copy number variation of CD24 could serve as a simple potential prognostic marker for identifying populations of interest for cancer treatment and risk subtype." (PMID 32370233, 2020). "Accumulating evidence has found an association between CD24 and cancer chemosensitivity." (PMID 32394616, 2020). "Molecules detected on the GSCs included those associated with the cancer stem cell phenotype (CD24, CD44 and CD90), as well as widely expressed cell surface molecules, such as major histocompatibility complex (MHC) class I (and β2‐microglobulin), CD71 and CD98, as expected." (PMID 31784984, 2020).